CD38 (CD38 molecule)
Diseases named in the same sentence as CD38 in open-access papers (continued):
Sharing a sentence is not in itself a finding about the gene and the disease.
multiple myeloma (continued). "The results confirm high level of CD38 expression by established tumor cell lines derived from multiple myeloma (LP-1) and Burkitt’s lymphoma (CA46, Daudi)." (PMID 29084989, 2017). "CD38 expression is relatively low on the cell membrane of these cells when compared with malignant plasma cells from multiple myeloma patients." (PMID 31548533, 2017). "In a similar fashion as occurred in multiple myeloma cells overexpressing CD38, isatuximab preferentially targets CD38high-expressing Tregs of patient MM cells." (PMID 31548533, 2017). "CD38 is uniformly overexpressed in all stages of myeloma, including on myeloma plasma cell precursors and possibly myeloma stem cells." (PMID 29900019, 2017). "A similar fusion construct of a monomeric CD38-specific nanobody with PE38 resulted in highly selective cytotoxicity against multiple myeloma cell lines and patient-derived multiple myeloma cells." (PMID 29213270, 2017). "In 2015, the U.S. Food and Drug Administration (FDA) approved three new therapies for multiple myeloma, namely Ixazomib (an oral proteasome inhibitor), Daratumumab and Elotuzumab (monoclonal antibodies against CD38 and SLAMF7 respectively)." (PMID 27863374, 2017). "Daratumumab, a human IgG1-kappa monoclonal antibody, was the first naked CD38 monoclonal antibody to be further developed for clinical use following demonstration of promising anti-myeloma activity in preclinical studies with cell lines and animal models." (PMID 31548533, 2017). "Myeloma cells induce the generation of Tregs (iTreg) which also highly express CD38 in addition to other known Treg markers." (PMID 31548533, 2017). "Daratumumab is a humanized monoclonal anti-CD38 antibody that was shown, in pre-clinical studies, to have anti-myeloma activity through ADCC, complement-dependent cytotoxicity, and antibody-dependent phagocytosis." (PMID 27618026, 2016). "CD38, as a cell surface antigen is highly expressed in several hematologic malignancies including multiple myeloma (MM) and has been proven to be a good target for immunotherapy of the disease." (PMID 27251573, 2016). "12, 13, 14, 15, 16 However, the intensity and number of CD38 in lymphoma or myeloma cells are much higher than in AML cells." (PMID 28090317, 2016). "We found that CD38 expression on peripheral and BM lymphocytes is approximately 100-fold less than that of plasma cells and myeloma blasts." (PMID 27611189, 2016). "CD38 is a regulator of cell adhesion and likely helps mediate a favorable stromal environment for myeloma cells." (PMID 27363832, 2016). "Daratumumab is the first-in-class human monoclonal antibody against CD38 cells which was studied in phase I/II trials for treatment of these patients with relapsed refractory multiple myeloma." (PMID 27752376, 2016). "There are several antigens with mAbs available relevant to plasma cell myeloma but currently only the antibodies to CD38, daratumumab and SAR650984, have proved their efficacy as myeloma treatment options." (PMID 27775669, 2016). "This is probably due to a higher content of antibodies targeting myeloma cells, as shown for anti-CD38." (PMID 27563813, 2016). "These transduced T cells were cytotoxic to B-lymphoma cells and myeloma cells expressing CD38.13, 14 In this study, we demonstrated that T cells transduced with anti-CD38-CAR also showed marked cytotoxicity against AML cells treated with ATRA." (PMID 28090317, 2016). "Daratumumab is a human monoclonal antibody that targets CD38, a cell surface protein that is overexpressed on multiple myeloma (MM) cells." (PMID 27363983, 2016). "Daratumumab is a human IgG1k monoclonal antibody against CD38, a cell surface protein that is prominently expressed on myeloma cells and plays numerous roles in myeloma tumorigenesis." (PMID 27363832, 2016). "In myeloma xenografts, treatment with 213Bi-anti-CD38-MAb suppressed tumor growth via induction of apoptosis in tumor tissue and significantly prolonged survival compared to controls." (PMID 25576914, 2015).
multiple myeloma (continued). "Multiple myeloma is a neoplastic expansion of plasma cells, whose plasma membranes express the highest epitope density of CD38, the ectoenzyme which consumes extracellular NAD+ with greatest efficiency." (PMID 26393653, 2015). "Daratumumab (DARA) is a human CD38-specific IgG1 antibody that is in clinical development for the treatment of multiple myeloma (MM)." (PMID 25760767, 2015). "Downregulation of CD138, which is one of the early markers of apoptosis in myeloma cells and the percentage of CD38+/CD138Bright primary MM cells as well as the amount of viable, apoptotic and dead cells were assessed simultaneously by flow cytometry." (PMID 26378933, 2015). "One advantage of using multiple myeloma (MM), a neoplastic expansion of plasma cells, as a model is that MM cells express high levels of surface CD38." (PMID 26393653, 2015). "The phenotype of MV is now under extended cytofluorimetric analysis by using mAbs specific for selected ectoenzymes that assist CD38 in regulating adenosine levels in the myeloma niche." (PMID 26393653, 2015). "Ligation of CD38 by DARA led to important effects on the myeloma cytoskeleton, with a re-distribution of the CD38 molecules and formation of distinct polar aggregates." (PMID 26393653, 2015). "Treatment with 213Bi-anti-CD38-MAb induced cell death in myeloma cells dependent on the individual CD38 expression level in each cell line, i.e. effects were significantly higher in cells with high CD38 expression." (PMID 25576914, 2015). "While the expression of CD38 by human myeloma cells has been long-established, the molecule’s role in the production of ADO is a less familiar concept." (PMID 26393653, 2015). "CD38 was successively selected by pharma companies as an ideal target for treating human multiple myeloma with specific monoclonal antibodies (mAbs), also in virtue of its favorable expression during ontogenesis." (PMID 26393653, 2015). "CD38, a surface receptor that controls signals in immunocompetent cells, is densely expressed by cells of multiple myeloma (MM)." (PMID 24489445, 2013). "The percentage of myeloma cells or PCs in BM mononuclear cells based on morphologic examination is almost the same as that of CD38-bright fractions measured by FC." (PMID 23021410, 2012). "While KYMM-1 expresses low levels of CD138, it is still considered a myeloma cell line, since it expresses high levels of CD38 and the cytoplasmic kappa light chain, and lacks CD19 expression and the EB virus genome." (PMID 22766978, 2012). "It has therefore been confirmed that normal PCs and myeloma cells are located in the CD38-bright fractions stained with CD38 antibodies." (PMID 23021410, 2012). "Profiling of CD38+CD138+CD45- myeloma cells isolated from patients by FACS confirmed the expression of the chemokine receptor CCR2." (PMID 21943176, 2011). "CD38 is a multifunctional enzyme that plays a pivotal role in NAD+ metabolism and calcium signaling, and its abnormal activity is closely associated with multiple myeloma, age-related metabolic decline, neurodegenerative diseases, and other disorders." (PMID 41828851, 2026). "Multiple myeloma (MM) remains an incurable plasma cell malignancy characterized by recurrent relapses and eventual refractoriness to standard agents, including proteasome inhibitors (PIs), immunomodulatory drugs (IMiDs), and anti-CD38 monoclonal antibodies." (PMID 41651798, 2026). "The markedly high uptake rates of our two types of EVs in non‐tumour cells might explain the lack of significant differences in uptake efficiency between EVs and CD38‐EVs in myeloma cells in the co‐culture systems." (PMID 40317915, 2025). "Future studies integrating proteasome inhibitors or next-generation myeloma agents (e.g., anti-CD38 antibodies, bispecifics) may further optimize outcomes in such rare composite cases." (PMID 41357603, 2025). "CD38-directed treatment of myeloma is described to inhibit antibody production after vaccination." (PMID 41050077, 2025).
multiple myeloma (continued). "In addition, only a small percentage of multiple myeloma patients develop alloantibodies against red blood cell antigens, as shown by results of the present study (1.94% before starting anti-CD38) and others." (PMID 40869587, 2025). "Overexpression of CD38 in lymphoma, multiple myeloma, and leukemia can be targeted with theranostic pairs of the monoclonal antibodies daratumumab or isatuximab with a variety of imaging radionuclides (68Ga, 64Cu, 99mTc, 89Zr) and therapeutic radionuclides (177Lu, 225Ac, 90Y, 212Pb, 211At)." (PMID 41344832, 2025). "Isatuximab is a CD38-targeting monoclonal antibody that exerts its anti-myeloma effects through multiple mechanisms, including antibody-dependent cellular cytotoxicity, complement-dependent cytotoxicity, antibody-dependent cellular phagocytosis, and direct induction of apoptosis." (PMID 40124649, 2025). "CD38 antibodies are now the backbone of multiple myeloma therapy." (PMID 40282438, 2025). "This may occur via Darwinian selection, where a differential death rate under Dara treatment leads to a relative increase in myeloma cells with low CD38 expression." (PMID 40788967, 2025). "Belatacept is currently involved in a pilot, phase I/II clinical trial (ATTAIN) to desensitize kidney transplant candidates with calculated Panel Reactive Antibody (cPRA) values ≥ 99.9%, together with daratumumab, a CD38 monoclonal antibody used in multiple myeloma." (PMID 40429403, 2025). "Recent studies have further established that CD38 monoclonal antibodies, such as daratumumab and isatuximab, can induce apoptosis of myeloma cells, promote clonal T-cell expansion, and modulate the tumor immune microenvironment, thus supporting their role as effective immunotherapeutic agents." (PMID 40529366, 2025). "The long physical half-life of 89Zr aligns with the extended biological half-life of monoclonal antibodies (~14 days in humans and ~7-8 days in mice), making 89Zr-daratumumab an ideal Cerenkov source for optimizing RaST and monitoring responses in CD38-overexpressing myeloma cells." (PMID 41041064, 2025). "Prior research in multiple myeloma showed αCD38 antibody efficacy relies on CD38 expression." (PMID 40057636, 2025). "Other treatments may include daratumumab, which is a monoclonal antibody targeting CD38 and used for multiple myeloma treatment." (PMID 41541959, 2025). "However, low CD38 levels on myeloma cells is a transient effect and it has already been shown that in 3 to 6 months after stopping treatment with anti-CD38 antibodies, CD38 expression on tumor plasma cells recovers." (PMID 39857790, 2025). "Similarly, hnCD16 was implemented in a BCMA-CAR-NK, enabling its use to target multiple myeloma together with the anti-CD38 antibody daratumumab." (PMID 41463563, 2025). "Despite substantial therapeutic progress achieved with proteasome inhibitors, immunomodulatory drugs, and anti-CD38 monoclonal antibodies, multiple myeloma remains incurable, and outcomes for triple-class-refractory patients remain dismal, with median survival below one year." (PMID 41470115, 2025). "Studies analyzing MM cells from RRMM patients suggest that prolonged anti-CD38 mAb exposure during post-ASCT maintenance may reduce CD38 expression on myeloma cells, limiting the efficacy of subsequent anti-CD38 therapies." (PMID 40786241, 2025). "The role of CD38 in multiple myeloma extends beyond its utility as a plasma cell marker." (PMID 40144871, 2025). "CD38 is a promising tumor antigen with significant potential for the treatment of multiple myeloma." (PMID 39856752, 2025). "Although most pharmacokinetic data on daratumumab are derived from studies on multiple myeloma, these findings provide valuable insights into its pharmacokinetic behavior, which is expected to be similar in acute leukemias due to comparable CD38 expression and target-mediated clearance." (PMID 41373522, 2025).
multiple myeloma (continued). "A recent study examining the immune microenvironment in multiple myeloma, following treatment with CD38-targeted immunotherapy and proteasome/IMiD combination, showed that the expansion of monocytes, NK-cell activation, and depletion of T cells were associated with sustained MRD negativity." (PMID 40338204, 2025). "In another study, daratumumab plus lenalidomide and dexamethasone (D-Rd) downregulated CD38 expression in multiple myeloma (MM) patients compared to Rd, especially in NK cells, B cells, basophils, monocytes, and CD4+ T cells, with no significant change in CD8+ T cells." (PMID 40821821, 2025). "Hence, CD38 mAbs therapy, besides targeting CD38-positive myeloma cells, can also restore an immunologically functional BMME exerting appropriate anti-MM T-cell responses." (PMID 41567224, 2025). "Multiple myeloma cells were identified by CD38 and CD138 expression." (PMID 39699274, 2025). "Recently, the addition of anti‐CD38 monoclonal antibodies (mAbs) to the triplet regimen, comprising a proteasome inhibitor, an immunomodulatory agent, and a steroid, for transplant‐eligible newly diagnosed multiple myeloma (TENDMM) has shown promising results." (PMID 40176408, 2025). "Interestingly, the multiple myeloma therapeutic monoclonal antibody, Daratumumab, which targets CD38, showed protective effects on bone and decreased osteoclastogenesis." (PMID 41350493, 2025). "For example, in a study using CD38- or CD138-targeted liposomal NPs in myeloma models, the targeted particles demonstrated significantly higher in vivo tumor accumulation and cellular uptake compared to non-targeted forms, thereby validating NPs delivery within the bone marrow microenvironment." (PMID 41471085, 2025). "Despite major therapeutic advances over the past two decades with proteasome inhibitors, immunomodulatory drugs (IMiDs), and monoclonal antibodies targeting CD38, multiple myeloma remains largely incurable, with most patients eventually experiencing disease relapse and drug resistance." (PMID 41470115, 2025). "Dalertuximab, a humanized monoclonal antibody targeting CD38, has demonstrated anti-tumor activity and has been approved for the treatment of multiple myeloma by mediating antibody-dependent cellular cytotoxicity (ADCC) and modulating the tumor immune microenvironment." (PMID 40529366, 2025). "Additionally, isatuximab inhibits the extracellular enzymatic activity of CD38+ cells, altering calcium balance and exerting anti-myeloma effects." (PMID 40027122, 2025). "Preclinical evidence that CD38-CAR T cells are effective in the treatment of myeloma." (PMID 40078993, 2025). "This indicates that the role of CD38 in hematological malignancies and cancer has been extensively studied, likely due to its established involvement in conditions such as leukemia, lymphoma, and multiple myeloma." (PMID 40529366, 2025). "We showed that CD38‐EVs effectively targeted myeloma cells both in vitro and in vivo." (PMID 40317915, 2025). "Since CD38 is not only expressed on the surface of myeloma cells but also on some B lymphocytes, daratumumab may lead to lymphopenia." (PMID 41244911, 2025). "Daratumumab(Darzalex) is a human IgG1κ monoclonal antibody (mAb) that binds to the CD38 protein expressed on the surface of cells in a variety of hematological malignancies, including clonal plasma cells in multiple myeloma and AL amyloidosis, as well as in other cell and tissue types." (PMID 40589132, 2025). "If it was not used first-line, it ishighly effective in relapse and can be given either alone or with other agents(trials show daratumumab monotherapy yields ≈40% responses in AL).Another anti-CD38 antibody, isatuximab, is in clinical trials for refractory ALamyloidosis​." (PMID 41524065, 2025).
multiple myeloma (continued). "In conclusion, our study is the first to demonstrate that the R2-ISS holds its value as a simple prognostic algorithm for patients at the time of relapsed and/or refractory multiple myeloma and in the era of novel agents, including anti-CD38 monoclonal antibodies." (PMID 39609425, 2024). "Multiple myeloma is a haematological cancer characterised by the accumulation of clonal plasma cells in the bone marrow and is commonly treated with daratumumab, an anti-CD38 monoclonal antibody immunotherapy." (PMID 39411424, 2024). "CD38 inhibitors are primarily used for the treatment of myeloma and have shown promising results." (PMID 38348050, 2024). "CD38 knockdown followed by cell surface proteomics demonstrated no significant remodeling of the myeloma “surfaceome” after genetically induced loss of this antigen." (PMID 40453054, 2024). "In our final set of experiments related to targeting surface CD38, we were intrigued as to whether binding of a therapeutic mAb leads to specific cellular phenotypes within myeloma plasma cells." (PMID 40453054, 2024). "Also it gives a informative value for the treatment of some CD38 immune-related diseases, such as lymphoma and multiple myeloma." (PMID 38862726, 2024). "ISB 1442 thus represents a CD47-BsAb combining biparatopic targeting of a tumor associated antigen with engineered enhancement of antibody effector function to overcome potential resistance mechanisms that hamper treatment of myeloma with monospecific anti-CD38 antibodies." (PMID 38448430, 2024). "NK cells, the major effector cells of mAbs, exhibit CD38 expression, second only to myeloma cells." (PMID 38410372, 2024). "In this study, we have determined the effect of tinostamustine in increasing the expression of both CD38, the target of daratumumab, and ligands for NK cell-activating receptors on myeloma cells, and its effect in enhancing daratumumab’s efficacy in different preclinical models." (PMID 38731936, 2024). "Multiple myeloma (MM) accounts for 10% of all hematological malignancies, and is characterized by proliferation and accumulation in the bone marrow (BM) of clonal CD38+ CD138++ plasma cells and by overproduction of monoclonal proteins (M‐protein) leading to diffuse organ damage." (PMID 39034465, 2024). "CD38 monoclonal antibody daratumumab is a fully human IgG1 monoclonal antibody specifically targeting the CD38 molecule expressed on the surface of myeloma cells, exerting anti-myeloma activity through immune-mediated mechanisms, the direct induction of cell apoptosis, and immunomodulation." (PMID 39329948, 2024). "Similarly, in multiple myeloma, the expression levels of CD38 in myeloma cells determine the efficacy of CD38 mAb-mediated cytotoxicity." (PMID 38284882, 2024). "Furthermore, these optimizations will be evaluated in therapeutic settings to image the effects on CD38 expression following CD38-targeted therapy as well as other potent myeloma therapies." (PMID 38480650, 2024). "Furthermore, these findings suggest a scenario in which daratumumab facilitates the fratricide depletion of CD38 pos NK cells, potentially constraining the subsequent availability of immune effector cells in the fight against myeloma cells." (PMID 39030183, 2024). "An important finding from this study is the observation that cycling exercise induced a profound mobilisation of NK-cells expressing CD38, which could be considered counterproductive for myeloma patients receiving daratumumab." (PMID 39411424, 2024). "B cell maturation antigen (BCMA) and CD38 are identified as target antigens for multiple myelomas." (PMID 38281269, 2024). "According to these observations, several agents, such as all-trans retinoic acid (ATRA), immunomodulatory drugs (IMiDs), HDACis and DNMTis, may increase the expression of CD38 in myeloma cells and subsequently improve anti-CD38 treatments." (PMID 38731936, 2024). "Daratumumab targets CD38, a cell surface ectoenzyme highly expressed on myeloma plasma cells." (PMID 40453054, 2024).